EDN1 (endothelin 1)
Diseases named in the same sentence as EDN1 in open-access papers (continued):
Sharing a sentence is not in itself a finding about the gene and the disease.
chronic kidney disease (60 papers, 2012 to 2026). Impairment of the renal function secondary to chronic kidney damage persisting for three or more months. "The endothelin-1 (ET-1) system has been implicated in the development and progression of chronic kidney disease (CKD)." (PMID 33217985, 2020). "Also, polymorphisms of EDN1 can influence the age of onset of end-stage renal disease in ADPKD." (PMID 31907669, 2020). "Another relationship that was discovered is a correlation between initial plasma endothelin 1 concentrations and initial serum total protein concentrations in the chronic kidney disease cohort (n = 27; p = 0.04; r = −0.43)." (PMID 41517469, 2025). "EDN-1 expression is increased both in chronic kidney disease and after acute renal injury after ischemia-reperfusion (IRI)." (PMID 39408610, 2024). "Endothelin 1 and the ETAR have been implicated in multiple chronic kidney diseases, and receptor activation is strongly associated with activation of the canonical NF-κB inflammatory pathway." (PMID 38511222, 2024). "Endothelin-1 (ET-1) as well as angiotensin II (AngII) promote glomerular injury, tubulointerstitial inflammation and fibrosis leading to chronic kidney disease." (PMID 38271614, 2024). "Edn1 is important to the progression of chronic kidney disease and renal scarring, leading us to evaluate kidneys subjected to IRI at longer time-points for their expression of Edn1 and its receptors of relevance, Ednra and Ednrb." (PMID 33907245, 2021). "ESA increases the expression of endothelin-1 in resistance subcutaneous arteries from chronic kidney disease patients." (PMID 24391978, 2013). "PAR 1 and endothelin 1 were correlated, although only in the chronic kidney disease group." (PMID 41517469, 2025). "We also found a relationship between initial plasma endothelin 1 concentrations and serum albumin concentrations following 1 year (n = 27; p = 0.05; r = −0.4) and 2 years (n = 27; p = 0.05; r = −0.4) of monitoring in the chronic kidney disease cohort." (PMID 41517469, 2025). "Chronic renal insufficiency (CRI) is characterized by increased endothelin 1 (ET-1) synthesis." (PMID 32023824, 2020). "Among uremic substances, for example, endothelin-1, which is classified of moderate molecular weight, and para-cresyl sulfate, a protein-bound uremic toxin, were reported as candidate substances that cause itching in patients with chronic kidney disease (CKD)-associated pruritus (CKD-aP)." (PMID 31766242, 2019). "It is therefore possible that increased production of ROS could be a mechanism for AngII to induce endothelin-1 synthesis as occurs in the vascular dysfunction observed in the setting of chronic kidney disease." (PMID 28344559, 2017). "Endothelin 1 also correlated negatively with total protein and albumin levels at many different time points during the follow-up period in the chronic kidney disease cohort, suggesting that it could be a predictor of total protein and albumin levels in this group of patients." (PMID 41517469, 2025). "Perchloric acidosis increases the production of endothelin-1 and aldosterone, thus leading to tubulointerstitial inflammation and injury, thereby accelerating the progression of chronic kidney disease (CKD)." (PMID 35005032, 2021). "Endothelin 1 was supposed to be related to the clinical course of membranous nephropathy, FSGS, IgA nephropathy, and chronic kidney disease." (PMID 41517469, 2025). "The relationship between initial plasma endothelin 1 concentrations and initial plasma PAR 1 concentrations in the chronic kidney disease cohort was statistically significant (n = 27; p = 0.03; r = 0.41)." (PMID 41517469, 2025). "Endothelin-1 is a potent vasoconstrictor that had an important role in development of PAH, increase in endothelial activities has been reported in chronic renal failure." (PMID 36471276, 2022).
chronic kidney disease (continued). "Endothelin-1 (ET-1) has been shown to contribute to IgAN pathogenesis through activation of endothelin A (ETA) receptors, leading to vasoconstriction, podocyte injury, inflammation, and fibrosis which lead to the progression of chronic kidney disease." (PMID 38398259, 2024). "Moreover, studies on molecular models should be performed to find out what was first: chronic kidney disease’s influence on PAR 1 and endothelin 1, or whether these biomarkers modulate CKD (chronic kidney disease)." (PMID 41517469, 2025).
type 2 diabetes (58 papers, 2006 to 2026). "The Asn/Asn genotype of EDN1 was associated with a reduced risk of DR and with delayed onset of type 2 diabetes." (PMID 18806884, 2008). "In inflammatory conditions such as type 2 diabetes, insulin can increase endothelin-1 (ET-1) leading to vasoconstriction via the mitogen-activated protein kinase (MAPK) pathway." (PMID 40281528, 2025). "Endothelin-1 (ET-1) is a pro-fibrotic molecule mainly secreted by endothelial cells and its plasma levels are highly increased in patients affected by SSc and type 2 diabetes, contributing to the fibrotic process." (PMID 27846260, 2016). "Pycnogenol® has also been found to significantly lower plasma endothelin-1 in patients with type II diabetes." (PMID 18618008, 2008). "We have shown that endothelin-1 (ET-1) mediates increased MMP activity and associated vascular remodeling in Type 2 diabetes." (PMID 16503991, 2006). "Besides, it is no efficient in controlling parameters other than hemodynamic system (HbA1c, endothelin 1 serum level, high sensitivity C-reactive protein plasma level and interleukin six serum level) in type II diabetes patients." (PMID 36814496, 2023). "Curcumin could improve endothelial function and reduce oxidative stress and levels of inflammatory markers (IL-6, TNF alpha, endothelin-1) in type 2 diabetes patients and enhance the functions of β cells." (PMID 34069726, 2021). "The connection between well-known inflammatory markers such as C-reactive protein (CRP), IL-6, IL-8, TNF-α, and endothelin-1 and DAN has been established in patients with type 1 and type 2 diabetes." (PMID 40137134, 2025). "The type 2 diabetic patients had higher levels of the inflammatory and endothelial markers hs-CRP, endothelin-1, and sICAM-1." (PMID 23671849, 2013). "A recent study investigating vascular endothelial function and pulmonary function in patients with type 2 diabetes, found a strong correlation between DLCO and vascular endothelial function parameters (nitric oxide, r = 0.797, endothelin-1, r = – 0.787 and flow mediated dilatation, r = 0.700)." (PMID 37889308, 2023).
breast carcinoma (56 papers, 1995 to 2025). "As visualized in the analysis, CCN1, CCN2 and EDN1 were among the most robustly downregulated genes, and it is notable that all of these genes have been implicated in breast cancer development." (PMID 41145489, 2025). "Another potential causal factor of breast cancer cell mediated osteoblastic lesions is Endothelin-1 (ET-1)." (PMID 33203195, 2020). "Neprilysin, a cell-surface enzyme that cleaves and inactivates a number of substrates including endothelin-1 (ET1), has been implicated in breast cancer, but whether neprilysin promotes or inhibits breast cancer cell progression and metastasis is unclear." (PMID 26950599, 2016). "Breast cancer cells also produce endothelin-1 (ET-1) that activates osteoblasts, resulting in the accumulation of immature mineralized bone (sometimes termed osteoid), and suppresses osteoclast activity." (PMID 40724520, 2025). "EDN1 has been further investigated as a target for anti-vascular therapy in cancers such as gastric cancer, breast cancer, and colon cancer." (PMID 35896520, 2022). "Hypoxia has also been found to affect the expression of the gene encoding EDN1 in U87 glioma cells and the genes encoding PTGS2 and VEGFA in breast cancer and melanoma cells." (PMID 34098948, 2021). "Endothelin-1 can activate Runx2 and confer an osteomimetic phenotype in breast cancer cells, contributing to colonization and osteolysis." (PMID 33123472, 2020). "Consistently, Angiopoietin 1 (ANGPT1) in C1, and MMPs and Endothelin 1 (EDN1) in C2 had been reported to take part in prostate or breast cancer bone metastasis." (PMID 32750747, 2020). "We further demonstrate that breast cancer cells likely contribute to cardiomyocyte hypertrophy through the secretion of soluble factors and that at least one of these factors is endothelin-1." (PMID 32787791, 2020). "SOX4 positively regulates the endothelin-1 expression and facilitates endothelin-1 secretion in breast cancer." (PMID 33123472, 2020). "Among these secreted factors, endothelin-1 (ET-1) has garnered attention as a vital factor for the growth, progression and metastasis of breast cancer cells." (PMID 32787791, 2020). "One paper evaluated the in vitro synthesis of the anti-inflammatory cytokine IL-12, reporting that it is increased by the treatment of 4T1 mouse breast cancer cells with endothelin-1." (PMID 31847214, 2019). "At the molecular level overexpression of endothelin-1 is the biomarker for both—Flammer syndrome and breast cancer with particularly poor prognosis." (PMID 31739537, 2019). "In contrast, depolarization in response to endothelin-1 was very similar in VSMCs of breast cancer feed arteries (ΔVm = 24.0 mV) and control arteries (ΔVm = 24.2 mV)." (PMID 29566737, 2018). "Conversely, media stress during stimulation with endothelin-1 and elevated [K+] is similar between breast cancer and control arteries." (PMID 29566737, 2018). "In fact, media stress (wall tension divided by media thickness) was similar in breast cancer feed arteries and control arteries when maximally stimulated with endothelin-1 (300 nmol/L) or elevated [K+]o (80 mmol/L)." (PMID 29566737, 2018). "The ectopic secretion of proteins, known to be microenvironmental stimuli like SPARC and Endothelin 1, appeared to confer osteogenic traits to disseminated breast carcinoma cells, important for the attachment to bone matrix." (PMID 26703564, 2015). "Because we found that EDN3 expression is frequently lost in breast cancer tissues, we next compared EDN1, EDN2 and EDN3 mRNA expression in breast cell lines in parallel." (PMID 19527488, 2009). "So far, overexpressions of EDN1 and EDNRA were already reported as being associated with impaired survival in breast cancer." (PMID 19527488, 2009).
breast carcinoma (continued). "Because the downstream effects of EDNRB are likely affected by the presence of its major ligands, ET1 and ET3 (encoded for by EDN1 and EDN3, respectively), we also analyzed survival in breast cancer subtypes by relative combined expression of EDNRB/EDN3 and EDNRB/EDN1 mRNA." (PMID 32201539, 2020). "Overall, the findings of this study suggest that breast cancer cells play a greater role in inducing structural cardiac remodeling than previously appreciated and that tumor-derived endothelin-1 may play a pivotal role in this process." (PMID 32787791, 2020). "Although a previous study found that over-expressing and knocking down EDNRB in two breast cancer cell lines altered invasion toward endothelin-1 (ET1) 16, EDNRB-regulated invasion toward ET3 and isoform-specific effects on breast cancer invasion have not been widely studied." (PMID 32201539, 2020). "Finally, only one study evaluated IL-1α expression using an in vitro model where breast cancer cells were treated with an endothelin-1 (ET-1) receptor dual antagonist, showing a local increase in breast cancer cell secretions of IL-1α." (PMID 31847214, 2019). "In addition, breast cancer cells have also been found to produce endothelin-1 (ET-1), which activates osteoblast differentiation via suppression of dickkopf-1 (DKK-1) and increased wingless-related integration site (Wnt) signaling." (PMID 29867053, 2018). "Indeed, our findings support that vasomotor activity in response to locally accumulated vasodilator metabolites (e.g., H+) and paracrine signaling substances (e.g., endothelin-1) is preserved in breast cancer feed arteries." (PMID 29566737, 2018). "Breast cancer feed arteries are thin-walled and produce lower tension than control arteries of similar diameter in response to norepinephrine, thromboxane-analog U46619, endothelin-1, and depolarization with elevated [K+]." (PMID 29566737, 2018). "Breast cancer feed arteries responded with reduced vasocontraction compared to control arteries when exposed to norepinephrine, thromboxane analog U46619, endothelin-1, or increased [K+]o." (PMID 29566737, 2018). "Additionally, circulating levels of EDN-1 precursor have been suggested as a potential biomarker for the early diagnosis of breast cancer." (PMID 27708222, 2016). "Our primary study aim was to determine whether endothelin-1 (ET-1) expression in tumor and stroma predicts breast cancer relapse." (PMID 23844294, 2013). "EDN3 expression, in contrast to abundant EDN1 and EDN2 expression, becomes frequently inactivated by promoter methylation in human breast cancer, potentially causing aberrant activation of the ET-axis, which in turn may promote this disease." (PMID 19527488, 2009). "Therefore, upregulation of EDN1 appears to coincide with downregulation of EDN3 in breast cancer cell lines." (PMID 19527488, 2009). "A role similar to that of EDN1 has been described for EDN2 in human breast cancer." (PMID 19527488, 2009). "Notably, an ET-axis expression pattern similar to that of breast cancer was recently found in cervical cancer; that is, upregulation of EDN1, EDN2, EDNRA and EDNRB expression was accompanied by downregulation of EDN3 expression in cancerous cervix as compared with normal cervical epithelium." (PMID 19527488, 2009). "In line with the overexpression results, knocking down Roquin2 increased the mRNA levels of angiogenic genes, including ENG, EDN1, VEGFB, and PDGFC in breast cancer cells." (PMID 34345214, 2021). "In breast cancer cell LCN2 can induce HIF1A expression, which is an important transcriptional factor mediated EDN1 gene expression in endothelial cells." (PMID 32968110, 2020). "Further corroborating our findings, we found that mRNAs for CXCL16 as well as for IL8, CSF2, MMP9, EDN1 and CCL2 all were expressed at significantly higher levels in basal-like breast cancers as compared with luminal A tumours." (PMID 27725631, 2016).
breast carcinoma (continued). "Endothelin-1 (ET-1) and its receptors (ETAR and ETBR), referred to as the endothelin (ET) axis, are overexpressed in breast carcinomas and appear to influence tumour growth and progression." (PMID 15226779, 2004). "We have previously shown that HIF-1 promotes breast cancer growth and invasiveness through endothelin-1 but not VEGF expression." (PMID 37108039, 2023). "In Roquin2-overexpressing MDA-MB-468 and MCF7 cells, we found that proangiogenic factors mRNA, including PDGFC, ENG, EDN1, and VEGFB, were downregulated in two breast cancer cells, while the mRNA expression of antiangiogenic genes, including TIMP1/3, SERPINF1, and ANGPTL4 were upregulated." (PMID 34345214, 2021). "PTHrP is not the only growth factor released by metastatic breast cancer cells, which cause this alteration in RANKL: OPG, Wnt-family members, transforming growth-factor-β (TGFβ), endothelin-1 (ET-1) and bone morphogenetic proteins (BMPs) also play a key role." (PMID 32751181, 2020). "Correspondingly, vascular smooth muscle cell depolarizations and intracellular Ca2+ responses are attenuated in breast cancer feed arteries during norepinephrine but not during endothelin-1 stimulation." (PMID 29566737, 2018). "The VSMC intracellular Ca2+ response to endothelin-1 did not similarly differ between breast cancer feed arteries and control arteries, which is in line with the equivalent levels of endothelin-1-induced media stress." (PMID 29566737, 2018). "Conversely, hypoxia induces Endothelin 1, which upregulates SPARC, and these biological stimuli may be considered prognostic markers of bone metastasis in breast carcinoma patients." (PMID 27187355, 2016). "Also, Endothelin 1 and ETAR are expressed in breast carcinoma metastasizing to bone, even if the predictive value of this axis has not been clarified until now." (PMID 26703564, 2015). "EDN1 and PDGFC stem-loop sequences could be amplified in the groups pulled down with anti-GFP antibody but not the isotype IgG, suggesting that Roquin2 binds to the stem-loop in the 3'UTRs of angiogenic mRNAs inside breast cancer cells." (PMID 34345214, 2021). "Furthermore GPER also mediated the effect of endothelin-1 (ET-1) on HIF-1 expression in normoxic ER negative breast cancer cells." (PMID 29996493, 2018). "Despite our finding that EDN1 was one of the few genes commonly regulated by SOX4 in the different breast epithelial cell lines used in this study, future work will have to uncover whether this regulation is conserved in all breast cancer cells and subtypes." (PMID 30507376, 2018). "The research has also illustrated that MBP-1 suppresses the activity of endothelin-1 (ET-1), angiogenin (ANG), interleukin-8 (IL-8), MMP-9, placental growth factor (PGF) and vascular endothelial growth factor (VEGF), which all accelerate cell apoptosis in breast cancer cells (MCF-7)." (PMID 30518090, 2018). "We next investigated cellular signaling events linking receptor activation in VSMCs to vasocontraction in order to determine why media stress in breast cancer feed arteries is lower than in control arteries during norepinephrine-induced contractions but not during stimulation with endothelin-1." (PMID 29566737, 2018). "For dysplasia and breast carcinoma of Patients 5 and 4, Endothelin 1/ETAR axis showed intermediate (+/++) and negative values, respectively, while Patient 1 showed strong signals (+++/++++) in specimens of dysplastic tissue and bone metastasis, with breast carcinoma staining positively (++)." (PMID 26703564, 2015). "A recent study demonstrated abundant expression of EDN1 and EDN2 but complete absence of EDN3 expression in a representative set of human breast cancer cell lines." (PMID 19527488, 2009).